LOXL2 (lysyl oxidase like 2)
Diseases named in the same sentence as LOXL2 in open-access papers (continued):
Sharing a sentence is not in itself a finding about the gene and the disease.
pancreatic cancer (continued). "Herein, we found that salidroside suppressed hypoxia‐inducible factor 1 alpha (HIF‐1α) and lysyl oxidase‐like protein 2 (LOXL2) within human pancreatic cancer BxPC‐3 cells cultured both under normoxia and hypoxia condition." (PMID 31162697, 2020). "Our clinical data demonstrated that the overexpression of SP1 and LOXL2 correlates with poor prognosis in patients with pancreatic cancer." (PMID 30976063, 2019). "In clinical data, the co-overexpression of SP1 and LOXL2 significantly correlates with poor prognosis in patients with pancreatic cancer." (PMID 30976063, 2019). "This study aimed to explore the clinical implications of LOXL2 expression in pancreatic cancer (PC) in the context of EMT status." (PMID 29959362, 2018). "The present results support the notion that LOXL2 is involved in the maintenance of the mesenchymal phenotype in pancreatic cancer cells and are consistent with previous results in other studies." (PMID 27285767, 2016). "For instance, inhibition of LOXL2 has been shown to result in the reduced viability of pancreatic cancer cells and their increased sensitivity to chemotherapy." (PMID 27285767, 2016). "We analyzed the prognostic impact of LOXL2 in pancreatic cancer patients and investigated the role of LOXL2 in pancreatic cancer cell lines." (PMID 27285767, 2016). "To accomplish this, we examined pancreatic cancer tissue for LOXL2 expression via immunohistochemical (IHC) staining and evaluated the prognostic significance of LOXL2 for pancreatic cancer patients." (PMID 27285767, 2016). "Based on experimental evidence, LOXL2 has previously been proposed as a therapeutic target in the treatment of pancreatic cancer." (PMID 27285767, 2016). "Expression of LOXL2 was analyzed in a series of pancreatic cancer cell lines: MIA PaCa-2, PANC-1, AsPC-1, and BxPC-3." (PMID 27285767, 2016). "Immunohistochemical analysis was performed in samples from 80 patients and showed LOXL2 expression in 81.2% of patients with pancreatic cancer." (PMID 27285767, 2016). "Proteomic profiling detected the gene product of LOXL2 in pancreatic cancer cells as well as in the secretions of pancreatic cancers." (PMID 27285767, 2016). "After identification of LOXL2 expression in pancreatic cancer cell lines, LOXL2-silenced and LOXL2-overexpressed cell lines were used to perform transwell invasion and transendothelial migration assays." (PMID 27285767, 2016). "In conclusion, results from an IHC analysis of tumors demonstrated that LOXL2 is an independent marker for metastatic disease and death in patients with pancreatic cancer." (PMID 27285767, 2016). "It has been reported that LOXL2 is one of the most highly and specifically upregulated genes in pancreatic cancer, compared to normal pancreatic tissues." (PMID 27285767, 2016). "In this study, we aimed to confirm the role of LOXL2 in the increased invasiveness of pancreatic cancer cells and to evaluate the clinical impact of LOXL2 in patients with pancreatic cancer." (PMID 27285767, 2016). "Future experiments using genetically engineered mice with LOXL2-specific knockout in PSCs, or spontaneous pancreatic cancer mouse models, may provide more direct evidence of how increasing linear ECM alignment contributes to tumor progression." (PMID 40425551, 2025). "Stromal profiling in pancreatic cancer datasets identifies LOXL2-rich niches as protective barriers in primary tumors, whereas LOXL2 depletion in liver metastases correlates with accelerated progression, warranting reassessment of anti-stromal therapies targeting collagen remodeling." (PMID 40693266, 2025). "Collectively, our findings not only explained the poorer prognosis observed in aged pancreatic cancer patients but also revealed that MMA can promote LOXL2 expression in PSCs, increasing linear ECM alignment, and accelerate the progression of PDAC (Graphical Abstract 1)." (PMID 40425551, 2025).
pancreatic cancer (continued). "The molecular details of how tamoxifen decreases collagen organisation in the breast have not been investigated here, but preclinical data from a mouse pancreatic cancer model suggest that tamoxifen reduces collagen content and organisation in a lysyl oxidase-like 2 (LOX-L2)-dependent manner." (PMID 39593191, 2024). "Taken together, our results suggest LOXL2 has an important regulatory role in maintaining gemcitabine resistance and may be an effective therapeutic target to treat pancreatic cancer." (PMID 37737908, 2023). "Therefore, the results revealed an important role for LOXL2 in the resistance to gemcitabine of pancreatic cancer cells and provided an effective therapeutic target to treat pancreatic cancer." (PMID 37737908, 2023). "We could hypothesize that LOXL2 was overexpressed in tissues and cells of patients with gemcitabine-resistant pancreatic cancer based on confirmed results and that it would play an important role in the resistance-related mechanism." (PMID 37737908, 2023). "In pancreatic cancer, LOXL2 is involved in EMT induction, tumor progression, and gemcitabine resistance, but the underlying molecular mechanisms remain largely unknown." (PMID 34836938, 2021). "Nevertheless, this study indicates that SP1 may serve as a therapeutic target for selected patients with pancreatic cancer, especially if silenced together with LOXL2." (PMID 30976063, 2019). "Additionally, LOXL2 is one of the most specifically and highly expressed genes in pancreatic cancer." (PMID 30976063, 2019). "However, there is a paucity of clinical evidence regarding the role of LOXL2 and its functions in pancreatic cancer." (PMID 27285767, 2016). "Our results suggest the clinical value of LOXL2 as a therapeutic target in pancreatic cancer." (PMID 27285767, 2016). "This disparity necessitates further investigation of LOXL2 in pancreatic cancer." (PMID 27285767, 2016). "To identify whether the clinical significance of LOXL2 expression in pancreas cancer patients is associated with metastasis and EMT properties, we conducted an in vitro study of LOXL2 in pancreatic cancer cells." (PMID 27285767, 2016). "LOXL2 is up-regulated in human pancreatic cancer, and might be correlated with the regulation of different transcription factors associated with invasion and metastasis." (PMID 27285767, 2016). "However, the exact mechanism underlying LOXL2-mediated distant metastasis in pancreatic cancer has not been fully characterized." (PMID 38560567, 2024). "Therefore, we concluded that stemness could be positively modulated by LOXL2 in gemcitabine-resistant pancreatic cancer cells with the exception of KLF4 expression." (PMID 37737908, 2023). "Therefore, our data also support a therapeutic approach in which intracellular LOXL2 expression could be an effective target molecule for the improved survival of pancreatic cancer patients." (PMID 27285767, 2016). "Here, we investigated the mechanism of LOXL2 induction and the effect of LOXL2 on EMT and CSC in gemcitabine-resistant pancreatic cancer." (PMID 37737908, 2023). "Recently, inhibition of the enzyme lysyl oxidase-like 2 (LOXL2) by a humanized monoclonal antibody (simtuzumab) has been attempted in colorectal and pancreatic cancers in combination with FOLFIRI or gemcitabine, respectively." (PMID 38139365, 2023). "In gemcitabine-resistant pancreatic cancer, the EMT process was significantly inhibited when ZEB1 and LOXL2 were co-regulated." (PMID 37737908, 2023). "Among all the proteins that were analyzed (MMP3, KIF5B, SFRP2, and LOXL2), KIF5B and SFRP2 show promise as bona fide early pancreatic cancer biomarkers expressed in progressive stages of pancreatic cancer." (PMID 36002889, 2022). "Previously, several studies reported that LOXL2 induces EMT in breast, gastric, and pancreatic cancer cells, which is accompanied by the activation of FAK/Src pathway." (PMID 29113306, 2017).
pancreatic cancer (continued). "We found that LOXL2 plays an integral role in the promotion of EMT and the invasiveness of pancreatic cancer cells." (PMID 27285767, 2016). "LOXL2 plays an integral role in EMT promotion and invasiveness of pancreatic cancer cells." (PMID 38560567, 2024). "Simtuzumab has shown limited efficacy in patients with pancreatic cancer or KRAS-mutant colorectal cancer, which may be due to the indirect and weak blocking effect of simtuzumab on the interaction of LOXL2 with PEAR1." (PMID 39145451, 2024). "Therefore, here, we investigated the effect of SP1 on invasiveness and EMT in PDAC cells through LOXL2 regulation and evaluated the clinical impact of SP1 as a prognostic factor in patients with pancreatic cancer." (PMID 30976063, 2019). "Additionally, our in vitro study demonstrated that LOXL2 expression promotes EMT and the invasiveness of pancreatic cancer cell lines, a finding compatible with the results of previous in vitro studies." (PMID 27285767, 2016). "Very recently, it has been announced that LOXL2-blocking antibodies did not improve outcome in a phase two trial in advanced pancreatic cancer." (PMID 26077591, 2015). "In the current study, four pancreatic cancer biomarker candidates (SYCN, REG1B, AGR2 and LOXL2) delineated through our previous integrated proteomics analysis of cell line conditioned media and pancreatic juice, were validated in two sample sets of serum/plasma containing a total of 432 samples." (PMID 24007603, 2013). "Moreover, LOXL2 promotes the activation of FAK/SRC and is involved in regulation of expression of CDH1, Snail, and L1CAM, all of which are related to EMT and invasiveness of pancreatic tumor cells." (PMID 38560567, 2024). "Therefore, overexpression of LOXL2 and ZEB1 was confirmed, and simultaneous regulation of both could effectively inhibit the EMT process in gemcitabine-resistant pancreatic cancer." (PMID 37737908, 2023). "However, a phase II study using the LOXL2 inhibitor simtuzumab for pancreatic cancer did not confirm a significant effect." (PMID 37737908, 2023). "Moreover, LOXL2 contributes positively to the activation of FAK/SRC and influences the expressions of CDH1, Snail and L1CAM, which are all related to EMT and the invasiveness of pancreatic tumor cells." (PMID 27285767, 2016). "Moreover, in light of the promising role of LOXL2 in promoting the activation of EMT-related molecules that increase the aggressiveness of pancreatic cancer, it is noteworthy that LOXL2 was prominently expressed in the majority of pancreatic cancer tissues in our study." (PMID 27285767, 2016). "To further assess the link between high lysyl oxidase family expression and pancreatic cancer, we analyzed biobanked plasma from 12 patients with histologically confirmed PDAC (stage III and IV) and 30 age- and sex-matched healthy individuals with no clinical diagnosis of disease, for LOX and LOXL2." (PMID 37640930, 2023).
fibrosis (24 papers, 2016 to 2026). the formation of excess fibrous connective tissue in an organ or tissue in a reparative or reactive process. "Here, we investigated Lysyl oxidase like 2 (LOXL2) as a biomarker for graft fibrosis and dysfunction." (PMID 41607781, 2026). "PAT-1251 was tested in direct comparison to the anti-LOXL2 mAb AB0023 in the Mdr2−/− biliary fibrosis model of pre-established fibrosis." (PMID 41385725, 2026). "Several mechanisms of LOXL2 regulation have been proposed in cancer development and cardiac fibrosis." (PMID 37328872, 2023). "We aimed to assess the influence of metabolic syndrome in fibrosis regression (by liver-stiffness measurement and serological scores) and its relationship with the expression of lysyl oxidase-like-2 as a potential goal of antifibrotic therapy." (PMID 31426495, 2019). "Lysyl oxidase-like 2 (LOXL2), an enzyme promoting collagen cross-linking, is upregulated in the livers of animals with fibrosis and of diabetic patients with NAFLD and is essential in hepatic fibrogenesis." (PMID 30197624, 2018). "In contrast to lung tissue from control treated mice, LOX and LOXL2 were highly induced in the BLM-induced fibrosis model." (PMID 28273952, 2017). "Using the data set with 118 biopsies, there was a significant positive correlation between LOXL2+ cells and the percentage of fibrosis (Kendall Tau, p=0.002), as well as a significant association with the Banff IFTA score (interstitial fibrosis and tubular atrophy." (PMID 41607781, 2026). "Correspondingly, the use of LOXL2/LOXL3 inhibitor can reduce collagen oxidation and collagen crosslinking, which represents an innovative therapeutic approach for the treatment of fibrosis." (PMID 36968277, 2023). "GS-6624 is a humanized IgG4 monoclonal antibody that targets LoxL2, blocks the activity of LoxL2, reduces the production of ECM by myofibroblasts, and has shown good efficacy in treating fibrosis." (PMID 35147920, 2022). "The DSS/AIEC fibrosis model did not lead to a significant rise in insoluble collagen in either mouse strain, and fibrosis-associated Tgfb, Col1a, Loxl2 and Nox4 genes were either only slightly increased or not altered, and only minimally downregulated in Nox4−/− mice." (PMID 33059312, 2020). "Collectively, these results indicate a signalling cascade from LOXL2 to PI3Kα/AKT/mTORC1 and then to TGF-β2 to stimulate cardiac fibrosis." (PMID 27966531, 2016). "Background: we aimed to assess the influence of metabolic syndrome on fibrosis regression (using liver-stiffness measurement (LSM) and serological scores) and the relationship with the expression of lysyl oxidase-like-2 as a potential goal of antifibrotic therapy." (PMID 31426495, 2019). "In this study, we also studied the role of LOXL2 in the regression of post-SVR fibrosis, even though recently published human trials do not support the use of monoclonal antibody Simtuzumab in nonalcoholic steatohepatitis and primary sclerosing cholangitis." (PMID 31426495, 2019).
breast tumor (17 papers, 2013 to 2023). "Mechanistic studies in primary cell lines derived from PyMT-breast tumours identified the association of Loxl2 with increased levels of Snai1 and several cytokines that promote the generation of a premetastatic niche." (PMID 37762708, 2023). "In particular, breast tumor-derived lysyl oxidase-like 2 (LOXL2) was implicated in the activation of resident fibroblasts in C57Bl/6 breast carcinoma mouse model through the upregulation of α-SMA expression and the β3 integrin/FAK/AKT signaling." (PMID 33562737, 2021). "In breast tumour cells, secreted LOXL2 promotes ECM remodelling leading to increased stromal stiffness." (PMID 37762708, 2023). "LOXL2 also directly activates CAFs in a murine breast tumor model and is upregulated in cells seeded on dense, aligned collagen matrices." (PMID 35205605, 2022). "Similar to OSM, LOXL2 expression has been linked to a worse prognosis in IDC patients, and increased invasion and metastasis of breast tumor cells." (PMID 34011405, 2021). "For instance, LOXL2 contributes to the stabilization of transcription factor Snail1 to promote breast tumor progression." (PMID 31121900, 2019). "Together these data further support that the targeting of LOXL2 secreted from primary tumor cells is capable of delaying the growth of primary breast tumors in vivo." (PMID 28199967, 2017). "In these models we also see a similar significant reduction in intratumor vessel density, confirming that tumor-secreted LOXL2 promotes primary breast tumor angiogenesis and enhances primary tumor growth." (PMID 28199967, 2017). "Here we present the first data to show that selective targeting of LOXL2 using small molecule inhibitors is effective against primary breast tumor burden." (PMID 28199967, 2017). "This pattern of LOXL2 expression was previously reported to be present in basal breast tumors and was strongly correlated with distant metastasis incidence." (PMID 27655685, 2016). "The AMT inhibitors are selective for LOX/LOXL2 and led to a significant reduction in tumor growth and metastases in an in vivo model of transgenic LOX-dependent breast tumor mice." (PMID 33669630, 2021). "Lysyl oxidase, LOXL2, or LOXL4 expression in the primary breast tumor leads to pre-metastatic deposition of collagen I in the lungs of mice, favoring the formation of metastases in the lungs." (PMID 26539408, 2015). "In addition, they described that HIF-1α plays a critical role in collagen biogenesis in breast tumors by upregulating the expression of P4HA1, P4HA2, PLOD1, and PLOD2 hydroxylases as well as the lysyl oxidase family members LOX, LOXL2, and LOXL4." (PMID 37686617, 2023). "Previous studies have concluded that LOXL2 pro-metastatic action is intrinsic to breast tumor cells and mostly independent of the extracellular action of this protein on the ECM." (PMID 33669630, 2021).